RAD51 (RAD51 recombinase)
Diseases named in the same sentence as RAD51 in open-access papers (continued):
Sharing a sentence is not in itself a finding about the gene and the disease.
cancer (continued). "LSD1 inhibition increased the level of transcription-repressive mark H3K9me2 in BRCA1/2 and RAD51 promoter, thus downregulating transcription of these genes and subsequently inducing HR impairment in HR-proficient cancer." (PMID 37973845, 2023). "For example, increased RAD51 mRNA expression is frequently observed in multiple types of CSCs compared to differentiated cancer cells, and inhibition with resveratrol or siRNA knockdown reduces CSC viability." (PMID 36980782, 2023). "Recent studies have demonstrated that overexpression of RAD51 contributes to tumor cell development, progression, and drug resistance in various types of cancer." (PMID 36262061, 2023). "Patients whose cancer tissues showed high RAD51 expression, in comparison to low RAD51 expression, had a higher percentage of alcohol consumption (84.1% vs. 63.6%, P = 0.02)." (PMID 37798649, 2023). "It has recently been reported that KRAS mutant can promote Rad51 expression to increase the chemotherapy resistance of cancer cells, while inhibiting HDAC can down-regulate Rad51 to counteract Rad51-mediated resistance of cancer cells." (PMID 36793108, 2023). "Recognition of DSBs by Rad51 and genomic destabilization were largely reduced by Olaparib, while the DNA damage response and cancer cell death were effectively increased." (PMID 36706121, 2023). "It has been shown that increased levels of RAD51 in irradiated human tumor tissues correlate with increased resistance to chemoradiotherapy and poor prognosis in a variety of human cancers, including ESCC." (PMID 37558683, 2023). "RAD51 has been investigated as a therapeutic target in cancer treatment in recent years, and several small-molecule inhibitors of RAD51 have been reported." (PMID 37798649, 2023). "RAD51 overexpression has been reported to serve as a marker of poor prognosis in several cancer types." (PMID 37798649, 2023). "RAD51 silencing or pharmacological inhibition demonstrated antitumor activity in cancer cell progression and enhanced cell apoptosis and DNA damage." (PMID 37175611, 2023). "This occurs through the promotion of RAD51 binding to BRCA2 and the facilitation of RAD51 aggregation at DSBs, leading to radiation resistance in cancer cells." (PMID 38137461, 2023). "Results showed that expression of RAD51 was significantly different across immune subtypes in 11 cancer types." (PMID 35359409, 2022). "In this study, the analysis demonstrated the potential use of RAD51 as a sign of the multiple cancer types immune microenvironment and RAD51 can be a potential predictive biomarker for the response to immune therapy." (PMID 35359409, 2022). "Of note, HR proteins including BRCA1, BRCA2, and RAD51 have been reported to be suppressed by HDACi in a variety of cancers, sensitizing to PARPi." (PMID 35681619, 2022). "Our findings of the role of BMI1/RAD51 axis in reducing RS and mediating therapeutic resistance in breast CSCs open new ways to treat cancer." (PMID 35110528, 2022). "RAD51 is a clinical valuable biomarker for multiple cancer types, regarding its potential power for diagnosis, prognosis, and therapeutic prediction." (PMID 35359409, 2022). "In addition, data has suggested that RAD51 might associate with cancer immunity." (PMID 35359409, 2022). "The small molecule RS-1 was developed as an allosteric effector to exploit overexpression of RAD51 activity by further stimulating the formation of toxic RAD51 complexes on undamaged chromatin as a potential cancer therapy." (PMID 35463312, 2022). "RAD51 inhibitor potentiated cytotoxicity of DNA breaking agent in all cancer cell types tested in vitro as well as in a subcutaneous model of EAC." (PMID 36428789, 2022). "Our data indicated that increased RAD51 contributes to growth as well as spontaneous and chemotherapy-induced damage and destabilization of genetic material in cancer cells." (PMID 36428789, 2022).
cancer (continued). "One strength of the study is the use of TCGA and the analysis of different cancers, enabling us to have an overview of the biomarker value of RAD51 in cancers." (PMID 35359409, 2022). "Pre-mRNAs of different members of RAD51 are subjected to alternative splicing and are believed to have impacts on cancer progression." (PMID 35163785, 2022). "Nonetheless, the BRCA2-RAD51 interaction, as a cancer-related target, can be disrupted directly in the cytosol at the RAD51 recruitment stage." (PMID 35955488, 2022). "In this study, the bioinformatic data supported the potential values of RAD51 for clinical cancer management, regarding cancer diagnosis, prognosis, and therapeutic prediction." (PMID 35359409, 2022). "Depletion of RAD51 expression or inhibition heightened sensitivity to DSB inducing agents including IR in various cancer cells." (PMID 35463312, 2022). "Survival data suggested that altered RAD51 resulted in a worse overall survival in cancer patients, but the case number for altered groups was relatively small and the p-value was relatively large." (PMID 35359409, 2022). "The KM plotting of high and low RAD51 patients showed that 9 cancer types remained significant in log-rank analysis." (PMID 35359409, 2022). "Concerning the gene expression evaluation, CF33 showed basal expression of the BCRA1, ERB-B2, and RAD51 genes involved in cancer development and progression." (PMID 36288156, 2022). "The calculation showed that the TIDE of 9 cancer types was significantly different between RAD51 high and low groups." (PMID 35359409, 2022). "RAD51 knockdown in cancer cell lines inhibited DNA end resection and strand exchange activity (key steps in the initiation of HR) as well as spontaneous DNA breaks, whereas its overexpression increased DNA breaks and genomic instability." (PMID 36428789, 2022). "RAD51 and BRCA2 are two key HR players and are strongly associated with cancer onset and anticancer therapies." (PMID 35955488, 2022). "On the contrary, negative LASSO coefficients were found for the genes ADRB2, CRYAB, NR4A1, CMTM5, ZBTB16, SYNE3, and RAD51, which were downregulated in cancer compared with normal samples." (PMID 36552262, 2022). "Our work also reveals a broad antiproliferative response of cancer cells originating from various organs by RAD51 inhibition." (PMID 35646698, 2022). "It is known that to develop novel inhibitors targeting Rad51 acts as an important avenue to improve the effectiveness of chemo- or radiotherapy for cancer patients." (PMID 35220392, 2022). "Results in this study suggested that RAD51 can be a predictive factor for the response to immune therapy in multiple cancer types." (PMID 35359409, 2022). "The CTPI2-induced impairment of Rad51 foci resolution in irradiated cancer cells corroborate a disturbance of HR repair by SLC25A1 inhibition." (PMID 35869047, 2022). "An interesting finding was that RAD51 was distinguished and highly expressed in T cells in the cancer samples." (PMID 35359409, 2022). "Proliferating T cells was the cell type that expressed highest RAD51 across most of the cancer samples analyzed." (PMID 35359409, 2022). "We also evaluated the expression of BRCA-1 and RAD51, molecules involved in HR, an error-free DNA repairing pathway, which is essential for cancer cell integrity." (PMID 36012375, 2022). "On the other hand, RAD51 was positively correlated to immune scores in 6 cancer types but negatively correlated to immune scores in 9 cancer types." (PMID 35359409, 2022). "where RAD51 was positively correlated to T cell CD4+ Th1, T cell CD4+ TH2, and common lymphoid progenitor scores in most of the cancer types, especially T cell CD4+ TH2 which was strongly correlated with RAD51 in most of the cancer types." (PMID 35359409, 2022). "The development of either RAD51 inhibitors or modulators can be safe and effective for clinical use and it is an exciting approach for cancer therapy." (PMID 35463312, 2022).
cancer (continued). "In 5 cancer types, RAD51 was strongly and negatively associated with the majority of the XCELL scores, while in 3 cancer types, RAD51 was strongly and positively associated with the majority of the XCELL scores." (PMID 35359409, 2022). "Currently, several RAD51 inhibitors have been developed to further exploit the HDR pathway as a therapeutic target for cancer therapy." (PMID 35463312, 2022). "Inhibition of RAD51 reduced spontaneous and DNA breaking agent-induced DNA breaks and genomic instability whereas potentiated cytotoxicity of DNA breaking agents in all cancer cell types tested." (PMID 36428789, 2022). "RAD51 inhibitor also significantly potantiated cytotoxicity of DNA breaking agent in all cancer cell types tested in vitro." (PMID 36428789, 2022). "Overall, these data show that RAD51 contributes to spontaneous and chemotherapy-induced genomic instability in cancer." (PMID 36428789, 2022). "We demonstrate that elevated RAD51 Expression correlates with poor survival of cancer patients in all three cancer types tested." (PMID 36428789, 2022). "A group of new BLM inhibitors known as isaindigotone derivatives were shown to interfere with BLM/DNA interactions and control HRR by encouraging the accumulation of Rad51 in cancer cells." (PMID 36499126, 2022). "Due to the prominent role of RAD51 to maintain the genomic stability, we set out to identify a small molecule that would inhibit its biological function as a strategy for cancer therapy." (PMID 35646698, 2022). "To further investigate the inhibitory effect of Nanog on Rad51 in human cancer cells, we manipulated Rad51 expression in HeLa cells and found that gradual increase in Rad51 was well correlated with the extent of decrease in Nanog-activated γH2AX." (PMID 35220392, 2022). "Purpose of this study was to investigate role of RAD51 and its potential as therapeutic target in cancer." (PMID 36428789, 2022). "RAD51 is frequently overexpressed in cancer cells, thus RAD51 has emerged as a potentially useful target in cancer therapy." (PMID 35897913, 2022). "Since genetic instability is one of the hallmarks of cancer, the DNA repairer, RAD51, as a biomarker for the distinguishment of cancerness of a cell, appears to be particularly reliable." (PMID 35359409, 2022). "The anatomy plot of the gene expression profile of RAD51 across all tumor samples and paired normal tissues in females and males showed that RAD51 was overexpressed in cancer in most of the organs." (PMID 35359409, 2022). "Vector-mediated overexpression or direct protein delivery of either the full-length or C terminal domains of Nanog into somatic cancer cells achieved strong inhibitory effect on Rad51 activity." (PMID 35220392, 2022). "Collectively, we conclude that Nanog acts as an effective inhibitor of Rad51 both in mouse ES cells and human cancer cells." (PMID 35220392, 2022). "RAD51 inhibitor significantly potentiated cytotoxicity of CPT in all cancer cell types tested and the impact of RAD51 inhibitor on CPT-induced cytotoxicity was mostly synergistic." (PMID 36428789, 2022). "We have previously shown that a protein RAD51 and its corresponding activity, which maintain stability of genetic material (DNA) in normal cells, are dysregulated in cancer." (PMID 36428789, 2022). "Wwox absence leads to very early DSB-induced DNA end-resection and enhances pRPA, Rad51, Abraxas, Brca1, and CtIP foci formation beginning at 0.5 h post IR in mouse cells and even earlier end-resection in human cancer cells." (PMID 35409089, 2022). "The alteration of RAD51 during the cell cycle further indicated its critical role in regulating the cell cycle of cancer cells." (PMID 35359409, 2022). "A number of studies demonstrated the role of RAD51 in cancer progression and the levels of the RAD51 protein are elevated in many cancer cell lines and in primary tumors." (PMID 35163785, 2022).
cancer (continued). "Consistent with the presence of basal replication stress in cancer cells and the role of RAD51 in dealing with replication stress, some cancer cells overexpress RAD51, making it a potential novel target for anti-cancer therapies." (PMID 35969531, 2022). "This study compared the expression of RAD51 across all tumor types and normal tissues using TCGA and GTEx data to determine the overexpression of RAD51 in cancers." (PMID 35359409, 2022). "The Tumor Immune Dysfunction and Exclusion of 9 cancer types were different between RAD51 high and low groups." (PMID 35359409, 2022). "RAD51 is very frequently overexpressed in cancer and is considered a key protein that plays an important role in cancer cell development and survival." (PMID 36361910, 2022). "Determining the mechanisms of how Rad51 mediates tumor adaptation brings promising strategies for cancer treatment." (PMID 35875146, 2022). "Suppression of RAD51 in cancer cell lines inhibited HR-related strand exchange activity and spontaneous as well as DNA breaking agent-induced DNA breaks and genomic instability in live cell fraction." (PMID 36428789, 2022). "Proteins implicated in HR repair pathway were frequently mutated in human cancers, such as BRCA1/2, ATM/ATR, RAD51, FA proteins, and others." (PMID 35952757, 2022). "In contrast, overexpression of RAD51 is common in many cancers, including cervical, non-small cell lung, breast, ovarian and pancreatic cancers, melanoma and glioblastoma." (PMID 34316706, 2021). "Epithelial–mesenchymal transition-associated drug resistance, hypoxia-mediated drug tolerance, and drug resistance in cancer stem cells all involve RAD51." (PMID 33952262, 2021). "Nevertheless, RAD51 overexpression has been previously reported in BRCA1/2 mutant cancer cells exhibiting HRD phenotype." (PMID 34762643, 2021). "Rad51 is overproduced in several types of human cancers and multiple cancer cell lines, and contributes to their increased survival after DSB induction." (PMID 34157114, 2021). "Our findings uncovered the molecular mechanism of the bidirectional effect of VPA under IR treatment both in vitro and in vivo, VPA would be able to target RFWD3 and trigger Rad51 ubiquitination for cancer radiotherapy." (PMID 33842359, 2021). "Of note, PTX also reduced Rad51 expression in the vast majority of cancer cell lines utilized for the present study, thereby suggesting the potential link between the microtubules dynamic state and Rad51 expression." (PMID 33503939, 2021). "The role of RAD51 in several types of cancer has led many teams to develop inhibitors targeting this recombinase." (PMID 34576930, 2021). "This is the first report proposing a novel role of RAD51 as a potential transcriptional co-factor, capable of controlling genes that contribute to the autophagy pathway in cancer cells." (PMID 34067336, 2021). "Another interesting fact observed for 2-APCAs-treated cancer cells was the significant decrease of Rad51 recombinase." (PMID 33503939, 2021). "While PARPi are generally inefficient against HR-proficient tumors, it was shown that inhibiting the HR pathway with RAD51 shRNA or with small-molecule inhibitors disrupting the RAD51/BRCA2 interface sensitized cancer cells to PARPi." (PMID 34208492, 2021). "Several small-molecule RAD51 inhibitors have been developed to increase cancer cell sensitivity to chemo- and radiotherapy." (PMID 34208492, 2021). "In contrast, overactivation or overexpression of RAD51 has been described in different types of cancer." (PMID 34316706, 2021). "Consistent with that, RAD51 was shown to be overexpressed in different types of cancer, including triple-negative breast cancer." (PMID 34208492, 2021).
cancer (continued). "Strikingly, RAD51 is overexpressed in most cancer cells including NSCLC, and its overexpression generally leads to the genomic instability and resistance to DSB‐inducing therapies." (PMID 33439503, 2021). "Second, we found that the promoters of a specific gene set were significantly occupied by RAD51 in four different cancer cell lines." (PMID 34067336, 2021). "RAD51 has a multifaceted role in carcinogenesis, cancer progression, and anticancer drug resistance." (PMID 33952262, 2021). "Elevated RAD51 expression increases homologous recombination competency of cancer cells and contributes to drug resistance to DNA-damaging chemotherapies." (PMID 33952262, 2021). "More studies are needed to understand how SYCP3 interacts with both BRCA2 and RAD51 and the impact on the BRCA2-RAD51 interactions in cancer cells and meiotic cells." (PMID 34440403, 2021). "The DNA repair pathway homologous recombination (HR) repairs platinum‐induced damage, and the HR recombinase RAD51 is overexpressed in cancer." (PMID 33709473, 2021). "A class of isaindigotone derivatives as novel BLM inhibitors was reported to disrupt the BLM/DNA interactions and regulate HR repair by promoting accumulation of Rad51 in cancer cells." (PMID 34846107, 2021). "In this study, we investigated the novel role of RAD51 in regulating genes at the transcriptional level, by reanalyzing RAD51 ChIP-seq data in multiple cancer cell lines, such as GM12878, HepG2, K562, and MCF-7." (PMID 34067336, 2021). "Overexpression of RAD51 or RAD52 rescued the XAB2 defects and XAB2 loss was synthetically lethal with RAD52 inhibition, providing potential perspectives in cancer therapy." (PMID 34500463, 2021). "Collectively, these findings provide evidence supporting the further development of small-molecule inhibitors of the regulatory protein-protein interactions of RAD51 for cancer therapy through radiosensitisation." (PMID 33662256, 2021). "Additional evidence that RAD51 plays an important role in the radiation resistance of this cancer comes from several pre-clinical in vitro studies showing that inhibition of RAD51 increases radiation sensitivity of GBM cell lines." (PMID 34771522, 2021). "The inhibition of RAD51 is also utilized as a strategy to impair HR repair in cancer treatments wherein this pathway is important for cell survival." (PMID 34201502, 2021). "It was indicated by our work that Rad51 has a considerable relationship with the immune cells, particularly in B cells, CD8 + T cells, macrophage, dendritic cells and cancer-associated fibroblast." (PMID 34115569, 2021). "Through blocking this protein-protein interaction, CAM833 is able to prevent RAD51-mediated homologous recombination and thus potentiate cancer cells to damage by radiation or PARP1 inhibition." (PMID 33662256, 2021). "In another approach, primary cancer cells were subjected to ionizing radiation-induced damage and the HR response was accessed by the number of RAD51 nuclear foci." (PMID 34762643, 2021). "But the most remarkable pro-cancer RAD52 phenotype is seen in cancer cells deficient in any of the following DNA repair proteins: BRCA1, BRCA2, PALB2, XAB2 or RAD51 paralogs: RAD51B, RAD51C, RAD51D, XRCC2 and XRCC3." (PMID 34887904, 2021). "Dysfunction in “BRCAness” genes, such as RAD51 and CDK12, can also cause HRD and is an important pathway in the development of ovarian or breast cancer." (PMID 34711195, 2021). "Our findings demonstrated an unrecognized function of RAD51 in transcriptional regulation of genes, which is related to autophagy in cancers." (PMID 34067336, 2021). "Of note, a significant decrease of Rad51 recombinase expression was also observed for the majority of cancer cells treated with 2-APCA-III." (PMID 33503939, 2021). "It is shown that overexpression of the RAD51 protein is correlated with increased survival of cancer cells to cancer treatments." (PMID 34576930, 2021).